TLR4 (toll like receptor 4)
Diseases named in the same sentence as TLR4 in open-access papers (continued):
Sharing a sentence is not in itself a finding about the gene and the disease.
inflammation (continued). "Furthermore, our studies demonstrate that proteases in poultry dust induce, in addition to IL-8 and IL-6, other genes implicated in lung inflammation such as IL-1β, CCL2, ICAM-1, PTGS2 and TLR4 in alveolar as well as bronchiolar epithelial cells." (PMID 27770804, 2016). "LPS in turn is involved in the activation of toll-like receptor 4 (TLR4) in the Kupffer cells stimulating essential inflammatory cascade, which results in prolonged liver inflammation, liver damage, and impairment of insulin signaling by diminishing phosphorylation of the insulin receptor." (PMID 27367724, 2016). "In order to investigate whether feeding a HFD for 16 weeks induces cardiac inflammation, protein expression of major pro-inflammatory cytokines was quantified as direct or indirect measure of TLR4 signaling (i.e., IL-6/TNF-α and SOCS-3, respectively)." (PMID 26539824, 2015). "Moreover, one study showed that TLR-4 was capable of regulating the early onset of joint inflammation and cartilage destruction in a murine model of immune complex-mediated arthritis and was closely associated with cartilage destruction." (PMID 25377946, 2014). "Most notably, the TLR4-mediated signaling pathway for LPS, leading to the activation of various intracellular kinases, including MAPKs and transcription factors, appears to be critical for the development of vascular inflammation and diseases." (PMID 24723958, 2014). "Tlr4-/- mice displayed an intermediate phenotype, suggesting that both TLR4-dependent and –independent pathways that utilize the MyD88 adapter protein contribute to acute lung inflammation and injury following ischemia and reperfusion." (PMID 24146959, 2013). "The relationship between increased MIF levels in patients with UTI-related renal inflammation and TLR4 is, therefore, speculative." (PMID 23319831, 2012). "Therefore, the mechanism of understanding the role of the TLR4 signaling pathway in Dox-induced cardiac inflammation might be beneficial for developing a potential therapeutic strategy for Dox-induced cardiotoxicity in the near future." (PMID 37298770, 2023). "Moreover, DAMPs released from inflammatory cardiomyocytes may contribute to TLR4-mediated cardiac inflammation." (PMID 36555168, 2022). "Hence, we hypothesized that EVs released into conditioned medium of LPS-challenged macrophages may induce TLR4-mediated cardiac inflammation." (PMID 36555168, 2022). "Administration of TLR4 antagonists, such as TAK-242 and CLI-095, counteracted chronic stress, neonatal colonic inflammation, and neonatal CRD-induced VHS." (PMID 39749341, 2024). "Since lung inflammation is one of the most common concerns in COVID-19 patients, we wanted to test whether WS extract has the potential to inhibit LPS-induced inflammation in the lung-derived cell lines and in the mice model of acute lung inflammation in a TLR-4-dependent manner." (PMID 37377934, 2023). "TLR4 and NOD2, as key PRRs, and their recognition of MAMP have been shown to be a key event in the development of mammary inflammation." (PMID 36204322, 2022). "Past reports suggest that multiple signal transduction pathways, including TLR4/NF-κB, PI3K/Akt, JAK/STAT, and AMPK, are involved in mediating pulmonary inflammation." (PMID 36035204, 2022). "The western blot results showed that TLR4/MyD88/Traf6 was elevated after METH treatment, suggesting that METH treatment induced liver inflammation, and antibiotics pretreatment can reverse this elevation." (PMID 34381368, 2021). "We have shown that hepatic IR activates liver macrophages and induces toll-like receptor 4 (TLR4) or NLRP3 activation, which drives the innate immunity-mediated liver inflammation." (PMID 33288903, 2021). "There is a body of evidence supporting GM-CSF as an important mediator in lung inflammation by upregulating TLR2, TLR4, and CD14 expression, and by boosting IL-6 and IL-1β production from macrophages." (PMID 30013577, 2018).
inflammation (continued). "In the present study, we show for the first time that the macrophage polarization and cardiac inflammation in SAMP8 mice through activation of the M1 macrophage polarization and HMGB1-TLR2/TLR4 signaling pathways." (PMID 27070323, 2016). "Furthermore, recent evidences have shown that TLR4-mediated pathway can promote tubulointerstitial inflammation in DN, and TLR4 antagonist may slow the progression of DN by attenuating renal tubulointerstitial inflammation." (PMID 26347890, 2015). "Dexmedetomidine (10and 20 μg/kg) significantly decreased mortality and pulmonary inflammation of septic rats, as well as suppressed CLP-induced elevation ofTNF-α and IL-6 and inhibited TLR4/MyD88 expression and NF-κB activation." (PMID 23690665, 2013). "Here we utilized this model of PLN-induced lung inflammation to determine the contribution of TLR2 and TLR4 to PLN effects in vivo." (PMID 19956717, 2009). "In particular, in-depth investigation of lycopene regulation of intestinal TLR-4/NF-κB signaling pathway through direct establishment of LPS-induced intestinal inflammation has not been reported." (PMID 40077496, 2025). "It was indicated that TLR4 plays a critical role in bladder nociception and voiding dysfunction independent of bladder inflammation in IC/BPS model." (PMID 38415918, 2024). "GO-203 exacerbated TLR4/MyD88/NF-κB pathway activation in vivo, and NLRP3 inflammasome-mediated pyroptosis reduced in a mouse model of asthmatic neutrophil airway inflammation induced by OVA/LPS; these pathological changes were partially alleviated after TAK-242 application." (PMID 37880668, 2023). "In RA, hyperactivated macrophages increased the expression of toll-like receptors (TLRs), such as TLR2, TLR3, TLR4, and TLR7, which induce synovial inflammation and cartilage destruction by releasing chemokines, pro-inflammatory cytokines, and degradative enzymes have been recognized." (PMID 36172378, 2022). "RBP4 regulates macrophage foam cell formation and enhances chronic endothelial inflammation through the activation of macrophages, mediated through the c-Jun-N-terminal protein kinase (JNK) and Toll-like receptor 4 (TLR-4) pathways, along with the activation of NADPH oxidase and NF-Κb." (PMID 34758835, 2021). "Altogether, these results suggest that TLR4 does not directly influence lymphadenopathy in a DSS model of colonic inflammation but LPS does, and it does so in a TLR4-independent manner." (PMID 30972059, 2019). "MTV, that in itself did not cause ALI, exacerbated increases in alveolar-capillary permeability, histopathologic scoring and indices of pulmonary inflammation in mice that previously underwent CLP; the effects of this two-hit model were abrogated in TLR4−/− mice." (PMID 30445996, 2018). "While we have not analyzed the molecular mechanism leading to heart inflammation during MS, experimental data has shown that Toll-like receptor 4 (TLR4) stimulation by fatty acids promotes TNF-α, IL-6, and IL-1β gene expression." (PMID 29201273, 2017). "Furthermore, they suppress NLPR3 inflammasome activation to reduce IL-1β and TGF-β/Smads signaling via CD36-mediated TLR4/6-IRAK4/1 signaling in animal and cell models, exhibiting the alleviation of fructose-induced cardiac inflammation and fibrosis." (PMID 27270216, 2016). "The concept of endogenous TLR ligands amplifying host responses to inflammatory triggers is supported by our recent findings that highly purified LTA, which is an established TLR2 ligand, induces less profound lung inflammation not only in TLR2 KO mice, but also in TLR4 KO mice 47)." (PMID 19956717, 2009). "Using TLR2- and TLR4-deficient mice, we further demonstrated that PM2.5-induced increases in BAL cell counts, ROS, IL-6, and TNF-α were partially attenuated in TLR4 knockout mice, indicating a contributory but not exclusive role for TLR4 signaling in PM2.5-driven pulmonary inflammation." (PMID 41596147, 2026).
inflammation (continued). "In conclusion, NG-COS has better protective effect on LPS-induced systemic inflammation in mice compared to naringin and COS, and its mechanism may be related to the regulation of the TLR4/NF-κB signaling pathway to inhibit inflammatory response and improve oxidative stress injury." (PMID 38397553, 2024). "Based on our initial findings demonstrating that directly stimulating cardiomyocytes with 0.01 μg/mL LPS does not induce a proinflammatory response, we concluded that LPS, potentially remaining in the conditioned medium, does not contribute to TLR4-mediated cardiac inflammation." (PMID 36555168, 2022). "In addition, other danger signal receptors independently of STING or TLR9 may be activated leading to type I IFN/IFNAR-dependent pulmonary inflammation including MDA5/RIG-l, TLR4/MyD88, TLR7MyD88 or TLR8/MyD88,)." (PMID 31619733, 2019). "We have previously demonstrated that sensitization to allergens, with a TLR4 or TLR9 agonist, prevents the development of Th2 lung inflammation without shifting the lung inflammation towards a Th1/Th17 pattern." (PMID 34358159, 2021).
cardiovascular diseases (96 papers, 2009 to 2026). "TLR4 has also been implicated in age-related neurodegenerative diseases, adipose inflammation and poor glucose tolerance, and cardiovascular disease." (PMID 39261941, 2024). "Toll-like receptor 4 (TLR4) is an innate immune receptor that is implicated in several cardiovascular diseases." (PMID 37239362, 2023). "TLR2, TLR3, and TLR4 are the TLRs that are predominately expressed in cardiomyocytes and play a large role in mediating inflammatory responses that are associated with cardiovascular disease." (PMID 37034342, 2023). "Fourth, we need to extend our follow-up duration to verify the long-term effect of smoking cessation on TLR4 mRNA expression levels and the clinical manifestation of the associated cardiovascular diseases." (PMID 33995400, 2021). "In particular, a clinical study showed that TLR4 is associated with cardiac dysfunction in patients undergoing coronary artery bypass surgery, suggesting the relationship of TLR4 with human cardiovascular diseases." (PMID 34740366, 2021). "Three tag single‐nucleotide polymorphisms (rs2770150, rs10759931, and rs4986790) in TLR4 were studied on 222 unrelated patients with cardiovascular diseases and 190 healthy volunteers." (PMID 31328431, 2019). "Previous studies have also shown a possible association between the TLR4‐Asp299Gly polymorphism and cardiovascular diseases." (PMID 31328431, 2019). "This study also showed that the cumulative burden of cardiovascular disease was reduced by more than half, in patients with both 399Ile and 299Gly TLR-4 polymorphisms, as compared with the background population." (PMID 29367560, 2016). "Our findings suggest that LPS promotes rat aortic SMC proliferation associated with cardiovascular diseases, and a positive feedback regulation of VSMCs proliferation is mediated through TLR4/Rac1/Akt signaling pathway." (PMID 24667766, 2014). "Translocated lipopolysaccharide (LPS) activates monocytes via TLR4 and is hypothesized to increase cardiovascular disease risk in persons living with HIV." (PMID 36028574, 2022). "Therefore, we aimed to investigate the effects of TLR4 polymorphisms on cardiovascular diseases risk in the Saudi population." (PMID 31328431, 2019). "Toll‐like receptors play a substantial role in innate immunity and the effects of TLR4 genetic variants on cardiovascular diseases are still largely unknown." (PMID 31328431, 2019). "In cardiovascular disorders, the role of TLR-4 may be associated with its responsiveness to host ligands, such as heat shock proteins released upon myocardial damage, fibronectin and reactive oxidative species." (PMID 29367560, 2016). "A known human TLR4 polymorphism (TLR4 Asp299Gly) in which responsiveness to TLR4 ligands is diminished has been studied quite rigorously as possibly being associated with an attenuated risk of cardiovascular diseases." (PMID 26998496, 2016). "In humans, TLR4 up-regulation is implicated in cardiovascular diseases." (PMID 25071777, 2014). "TLR4 has been implicated in the development and progression of cardiovascular diseases." (PMID 22233532, 2012). "In the future, we may need to conduct large-scale prospective cohort studies to explore whether smoking cessation, with decreased the levels of TLR4 mRNA expression in PBMCs, will lead to a significant reduction in the risk of cardiovascular disease and the associated mortality." (PMID 33995400, 2021). "Likewise, SNPs in these regions of TLR4 have also been linked to an increased incidence of several diseases such as colon, breast, prostate, cervical cancer (2011), and cardiovascular disease." (PMID 31328431, 2019). "TLR4 exists in VSMCs, and may be implicated in restenosis, and therefore may make a fundamentally significant contribution to the crucial pathophysiological relationship between inflammation and cardiovascular disorders." (PMID 24667766, 2014).
cardiovascular diseases (continued). "Toll-like receptor 4 (TLR4) leads to many elderly-related cardiovascular diseases involving in cardiovascular damage." (PMID 41278503, 2025). "The Toll-like receptor 4 (TLR4) is also involved in the inflammatory response in cardiovascular diseases." (PMID 36937865, 2023). "Various pre-clinical and clinical models have shown the importance of TLR4 in promoting inflammation and oxidative stress in cardiovascular diseases." (PMID 37239362, 2023). "TLR4 mediates inflammatory responses by inducing the production of pro-inflammatory genes related to septic shock, acute lung injury, and cardiovascular disease." (PMID 37111237, 2023). "With these results, it is plausible to propose a peptidic approach for TLR4 modulation as a new innovative therapy to the treatment of TLR4-related cardiovascular diseases." (PMID 35433873, 2022). "We propose the plausibility of this peptidic approach for TLR4 modulation as a promising therapy relevant to the treatment of TLR4-related cardiovascular diseases." (PMID 35433873, 2022). "In cardiovascular diseases, TLR4 has protective and harmful effects on some systems, such as mediating various inflammatory effects of the aorta, arterioles, fat cells and macrophages." (PMID 35224064, 2022). "In the progression of cardiovascular disease, Toll-like receptor 4 signaling has been recognized to promote the release of MCP-1 from activated monocytes." (PMID 36409752, 2022). "One study suggested that heparan sulfate–TLR4-mediated monocyte/macrophage-induced inflammation contributes to the pathogenesis of cardiovascular disease in MPS I." (PMID 36556450, 2022). "The TLR4 response is closely related to the occurrence, development, and prognosis of cardiovascular diseases." (PMID 36014544, 2022). "In summary, our study indicates that targeting TLR4 is a potential therapeutic strategy for preventing aging-related cardiovascular disease." (PMID 34740366, 2021). "Our study indicates that targeting TLR4 is a potential therapeutic strategy for preventing aging-related cardiovascular disease." (PMID 34740366, 2021). "TLR4, the first characterized mammalian Toll-like receptor, is widely accepted to play an important role in facilitating inflammatory responses during cardiovascular disease." (PMID 34512865, 2021). "The TLR4 pathway has been reported to be related to chronic inflammation and the progression of a variety of diseases, such as diabetes, cardiovascular diseases, and even cancer." (PMID 34740366, 2021). "TLR4, the first identified TLR, has also been implicated in the development and progression of cardiovascular disease." (PMID 31316302, 2019). "This obviously makes TLR4 an interesting receptor to target for the prevention and/or treatment of cardiovascular diseases." (PMID 29170605, 2017). "An alternative strategy is the development of small molecule therapies that diffuse into arterial parenchyma and block the inflammatory response leading to MPS cardiovascular disease via inhibition of TLR4 signaling or pro-inflammatory cytokines." (PMID 26986213, 2016). "While exploring potential etiologies of MPS I cardiovascular disease, significant overexpression of the Toll-like receptor 4 gene, in addition to numerous cathepsin proteases and matrix metalloproteinases was observed." (PMID 26986213, 2016). "For cardiovascular diseases, Eritoran also showed some preclinical benefits and attenuated myocardial I/R injury by inhibiting TLR4." (PMID 22577589, 2012). "Reports indicate that TLR4 is involved in the development of several cardiovascular diseases." (PMID 39453113, 2024). "Previous studies have confirmed that effect of TLR4 on cardiovascular disease." (PMID 34025643, 2021). "At present, TLR4 has been identified as a crucial regulator in cardiovascular disease." (PMID 34120606, 2021).